MYD88 (MYD88 innate immune signal transduction adaptor)
Diseases named in the same sentence as MYD88 in open-access papers (continued):
Sharing a sentence is not in itself a finding about the gene and the disease.
leukemia (14 papers, 2013 to 2025). A malignant (clonal) hematologic disorder, involving hematopoietic stem cells and characterized by the presence of primitive or atypical myeloid or lymphoid cells in the bone marrow and the blood. "Collectively, these observations revealed that downregulation of Myd88 is associated with increased development of leukemia with a similar genetic profile as the leukemias observed in Pax5+/− mice and those from human patients." (PMID 37620322, 2023). "Some somatic mutations (as in MYD88) and chromosomal abnormalities (as del(13q) and trisomy 12) are mostly found in the all leukemic cells indicating that these alterations occurred early in leukemia genesis." (PMID 32708233, 2020). "To explore the relevance of our findings for human leukemia, we compared the role of Myd88 activity on mRNA expression in from tumor cells from patients with B-ALL28–31." (PMID 37620322, 2023). "Early induction of Myd88-independent Toll-like receptor 3 signaling results in a significant delay of leukemia development in Pax5+/− mice." (PMID 37620322, 2023). "Genetic reduction of Myd88 expression leads to a significant increase in leukemia incidence in Pax5+/−Myd88+/− mice through an inflammation-dependent mechanism." (PMID 37620322, 2023). "The advent of leukemia in Pax5+/−;Myd88+/− mice under natural infection exposure occurred at between 7 and 20 months of age, similar to the Pax5+/− group." (PMID 37620322, 2023). "Indeed, a preleukemic B-cell-dependent role was evidenced by an increase in B-ALL incidence upon Myd88 downregulation in the leukemia-prone Pax5+/− model." (PMID 37620322, 2023). "Furthermore, the TLR4/Myeloid differentiation primary response 88 (MyD88) signaling in the leukemic cells seems important for leukemia cell growth, disease development and chemosensitivity in human AML." (PMID 35163998, 2022). "Epinecidin-1 peptide also has been found to regulate the toll-like receptor (TLR)-2/MyD88 pathway in RAW264.7 macrophage and exert anticancer activity for leukemia U937 cells." (PMID 30915150, 2019). "Despite these defects, MyD88 was not required for graft-versus-leukemia activity, suggesting that MyD88 regulates effector function and survival without altering TCR-mediated tumor recognition." (PMID 40948803, 2025). "As immune disease-related genes, MYD88 (81.4%) and BCL10 (25.9%) in NF-ĸB signaling, CD79B (59.2%), PAX5 (22.2%), and BCR (7.4%) in B-cell development, and MYH11 (25.9%), RUNX1 (7.4%), and TET2 (7.4%) in leukemia were observed." (PMID 29937999, 2018). "However, whether TRIM24 or MYD88 plays a role in BETi resistance in leukemia has not been well determined." (PMID 37036970, 2023). "RNA levels of MYD88 are higher in KG1 cells than in 293T cell and several other leukemia cell lines such as K-562, HL-60 or U937 (data not shown)." (PMID 23976989, 2013).
multiple myeloma (14 papers, 2013 to 2023). "An early study in multiple myeloma cells showed that IFN‐γ promoted PD‐L1 expression through a MyD88‐, TRAF6‐ and MEK‐dependent pathway, and IFN‐γ activated transcription factor STAT1 partially via the MEK/ERK pathway." (PMID 28218497, 2017). "Conversely, the top-200 genes that negatively correlated with TOX exhibited significant overlap with post-GC B-cell signatures, including down-regulated signatures in FL (compared to reactive lymph node or NMZL either), IRF4 programme in myeloma and plasma cells and MYD88 up-regulated transcriptome." (PMID 32106280, 2020). "Plasma cells from multiple myeloma patients express PD-L1 and increase expression after stimulation with IFN-γ and TLR ligands via a myeloid differentiation primary response gene 88/tumor necrosis factor receptor associated factor 6 (MYD88/TRAF6)-, MEK-dependent pathway." (PMID 28484456, 2017). "B7-H1 expression was enhanced on malignant plasma cells from multiple myeloma patients by IFN-γ and Toll-like receptor stimulation via MEK/ERK-dependent and MyD88/TRAF6-dependent pathways and can inhibit T-cell responses." (PMID 23737812, 2013). "Additionally, we noted the presence of the MYD88 L265P in patients with IgM or IgG-MGUS, as well as in MGUS patients from families with multiple myeloma." (PMID 26352266, 2015). "The MYD88 L265P mutation has been reported to be expressed in both WM and IgM MGUS patients but not myeloma." (PMID 25028614, 2014). "By means of AS-PCR, the MYD88 L265P mutation is detectable in 93% of patients with WM and in 54% with IgM-MGUS but is absent in myeloma samples." (PMID 25028614, 2014). "When we retrospectively reviewed five MYD88-negative cases, one patient presented with 5.7% lymphocytes and 32.9% plasma cells in BM aspirates with the IGH rearrangement and 1q amplification, suggesting that a diagnosis of IgM plasma cell myeloma might be considered." (PMID 24895570, 2014).
liver cancer (13 papers, 2018 to 2024). An epithelial or non-epithelial malignant neoplasm that arises from the liver. "However, the underlying mechanism by which MyD88 in myofibroblasts regulates NAFLD-associated liver cancer development remains unknown." (PMID 38291436, 2024). "In myofibroblasts, MyD88 inhibits hepatocarcinogenesis by preventing aerobic glycolysis of liver cancer cells in DEN/CCl4-induced HCC." (PMID 38291436, 2024). "Myofibroblast-specific MyD88 deletion decreased fat accumulation and tumor incidence in HFD-induced NAFLD and DEN/HFD-induced liver cancer." (PMID 38291436, 2024). "Recently, we also found that MyD88 in HSCs/myofibroblasts promoted the progress of DEN/CCl4-induced fibrosis-related HCC via CCL20 secretion and promoted the aerobic glycolysis of liver cancer cells." (PMID 38291436, 2024). "However, there is limited information about the function of MyD88 in myofibroblasts in NAFLD and NAFLD-related liver cancer." (PMID 38291436, 2024). "For example, mice lacking Myd88 displayed a reduction in hepatocarcinogenesis in DEN-induced liver cancer." (PMID 37968706, 2023). "MyD88 signaling induces translocation of NF-κB to the nucleus and the transcription of cytokines such as IL-6 and TNF-α that are essential for the initiation of DEN-induced liver cancer." (PMID 31049358, 2019). "We observed significant antitumor activity in a DEN-induced HCC model with MyD88 ASOs even though the ASO treatment started 6 months after DEN injection, suggesting that MyD88 might function as a major tumor promoter throughout the progression of liver cancer." (PMID 31303442, 2019).
lupus nephritis (13 papers, 2012 to 2025). Glomerulonephritis in the context of systemic lupus erythematosus. "Our study demonstrates that VEGFR-3 inhibition reduces TLR7/MyD88/IFN-α signaling in lupus nephritis." (PMID 40651955, 2025). "In contrast, genetic depletion of MyD88 in B cells impairs the secretion of antinuclear antibodies and abrogates lupus nephritis because activated B cells contribute to both antibody-dependent and -independent renal T cell infiltrates in MRL/lpr mice." (PMID 29650017, 2018). "There are four SLEmetaSig100 genes (NFAIP3, IRAK4, MYD88, TLR4) in NF-kappa B signaling pathway that have been implicated in the pathogenesis of lupus nephritis coupled with upregulation of inflammatory cytokines." (PMID 29975701, 2018). "Moreover, they establish HMGB1, TLR4, and MYD88 as novel molecular markers for NETs-mediated renal inflammatory damage in lupus nephritis, providing new targets for the prevention, diagnosis, and treatment of this condition." (PMID 41208960, 2025). "Interestingly, in MRL/lpr mice TLR/MyD88 signaling in dendritic cells is dispensable for the development of autoantibody production and lupus nephritis." (PMID 29650017, 2018). "One study using MyD88-deficient MRL/lpr mice showed no obvious change of lupus nephritis, while another study using DC-specific MyD88 and Lyn double-deficient mice showed attenuated lupus disease compared to DC-specific Lyn-deficient mice." (PMID 27034965, 2016). "Our results support the notion that IRAK1 and/or IRAK4 are attractive targets for the development of drugs to prevent, and perhaps treat, lupus nephritis and other autoinflammatory diseases caused by the decreased ability of ABIN1 or other proteins to restrict the strength of MyD88 signaling." (PMID 27807192, 2016). "CD19-cre mediated MyD88 depletion in B cells ameliorates lupus nephritis in MRL-Faslpr/lpr mice." (PMID 26068236, 2015). "The lupus nephritis that develops in TANK-KO mice, and which is driven by hyperactivation of the MyD88 signaling network, was similarly prevented by crossing to IL-6–KO mice." (PMID 27807192, 2016).
mastitis (13 papers, 2015 to 2025). Inflammation of breast tissue during lactation or postpartum due to an obstructed duct or infection. "The mRNA levels of TLR4, MyD88, IKKβ, and NF-κB p65 were significantly different between the model group and the non-mastitis group (p < 0.01)." (PMID 40266913, 2025). "The TLRs, when activated by mastitis-induced bacteria, pass the signal to MYD88, which is considered the critical immune regulator adapter molecule against various pathogens." (PMID 32927884, 2020). "The most in-depth mechanism showed that polydatin decreased the expression of TLR2 and MyD88, which further suppressed the level of NF-κB in mammary epithelial cells of S. aureus- induced mastitis." (PMID 32927884, 2020). "Moreover, when we analyzed introgression in the Nera di Arbus, we found that some of the PNAbv regions harbor QTLs and genes (e.g., C9, FYB, and MYD88) related to somatic cell count and mastitis resistance, traits essential for udder health." (PMID 41273432, 2025). "In both S. aureus-positive and S. chromogenes-positive cows, the DE snoRNAs were correlated with several immune and inflammatory genes (e.g., IL1R, IL18R1, STAT3, NFKB2, MYD88, VEGFA and CD40), all of which have been reported in several studies to be associated to mastitis." (PMID 40936092, 2025). "However, miRNAs are an addition to the negative regulation of inflammation, and they are a feedback system in which a bacterial component, as in mastitis, induces NF-kB through an MYd88-dependent pathway, resulting in miR-146a upregulation." (PMID 38643124, 2024). "The cell membrane receptor TLR4 recognizes exogenous stimuli such as lipopolysaccharide from E. coli, and the signal is transmitted through MyD88, activates NF-κB, and then modulates many of the pro-inflammatory cytokines and chemokine transcripts that contribute to the development of mastitis." (PMID 35893774, 2022). "Moreover, significantly higher expression levels of MYD88 gene have been observed in bovine mastitis tissue." (PMID 33578642, 2021). "In addition, based on published literature, we concluded that TLR4, IL-1β, IL-6, TNF-α and MYD88 are key players in NF-κB signaling and also have an essential role in mastitis development." (PMID 32927884, 2020). "Taken together, these data suggest that the immune response of Chinese Holstein cattle with mastitis may occur by a MyD88-dependent channel that is mediated by TLR4/ NF-κB." (PMID 25706977, 2015). "In addition, TLR4, IL-1β, IL-6, TNF-α, MYD88 and NF-κB might be a useful addition as markers in mastitis control strategies." (PMID 32927884, 2020). "Levels of IFN-γ, IL-4, TNF-α, MYD88, CCL5, TLR4, TLR9, LTF, PRLR, Keap1 and OXSR1 genes expression were significantly up-regulated in ewes affected with mastitis than resistant ones." (PMID 40542007, 2025). "Mastitis-affected ewes had considerably higher levels of IFN-γ, IL-4, TNF-α, MYD88, CCL5, TLR4, TLR9, LTF, and PRLR gene expression than resistant ones." (PMID 40542007, 2025). "It is thus clear that indirubin treatment of lipopolysaccharide induced mastitis in a mouse model and activity in mouse mammary epithelial cells via bated TLR4 and its two main Myd88-dependent pathways, NF-κB and MAPK." (PMID 28255203, 2017). "Some immune-related genes, such as ITGB6, MYD88, ADA, ACKR1, and TNFRSF1B, and their potential relationships with mastitis were highlighted." (PMID 27459697, 2016). "Statistical analysis of transcript and protein level expression changes indicated that 10 genes, namely TLR4, MyD88, IL-6, and IL-10, were up-regulated, while, CD14, TNF-α, MD-2, IL-β, NF-κB, and IL-12 were significantly down-regulated in mastitis tissue in comparison with normal tissue." (PMID 25706977, 2015). "Additionally, some PNAbv regions harbor genes related to mastitis, such as C9, FYB, and MYD88." (PMID 41273432, 2025).
mastitis (continued). "In the current investigation, qRT-PCR was used to measure the levels of antioxidant (CAT, GPX1, Keap1, OXSR1, ATOX1, GST, and Nrf2) and immune (IFN-γ, IL-4, TNF-α, MYD88, CCL5, TLR4, TLR9, LTF, and PRLR) genes in Barki ewes that were resistant and non-resistant to mastitis." (PMID 40542007, 2025).
myocarditis (13 papers, 2011 to 2025). Myocarditis is a condition that is characterized by inflammation of the heart muscle (myocardium). "As such, MyD-88−/− patients have a reduced risk of developing myocarditis as compared to MyD-88+/+ individuals if started on ICI therapy." (PMID 36204564, 2022). "DCs loaded with a heart-specific self-peptide induce T-cell mediated myocarditis through myeloid differentiation primary response 88 (MyD88)/IL-1 signalling in the bone marrow compartment." (PMID 40264510, 2025). "Patients with myocarditis have high heart expression of MyD88, CD3+ lymphocytes and collagen fibers and these phenomena was recently seen in patients with SARS-CoV-2 infection." (PMID 34178667, 2021). "MyD-88 gene upregulates the genetic transcription of pro-inflammatory cytokines to flare inflammatory reactions and thus, plays a pivotal role in promoting fibrosis and progression toward myocarditis or heart failure." (PMID 36204564, 2022). "However, the most significant effects were seen by analyzing NLRP3 and MyD88, both involved in myocarditis and several cardiovascular diseases." (PMID 33086484, 2020). "Similarly, in comparison to WT littermates, MyD88−/− mice were protected from myocarditis after immunization with α-myosin heavy chain-derived peptide (MyHC-α) and complete Freund's adjuvant." (PMID 21977329, 2011). "On the contrary, patients who were MyD-88−/− had a diminished autoimmune response and thus were much less likely to develop myocarditis regardless of the triggers that patients were subjected to." (PMID 36204564, 2022).
Allergy (12 papers, 2016 to 2025). An allergy is an immune response or reaction to substances that are usually not harmful. "Interestingly, MyD88 is a critical signaling node of lung macrophages, highlighting the potential of macrophages as a driver of reductions in allergy associated with the hygiene hypothesis." (PMID 38983858, 2024). "In various infectious and allergic diseases, the IL-33/ST2 axis has been implicated in transducing proinflammatory signals to immune cells via myeloid differentiation primary response 88 (MyD88)-related pathways." (PMID 38548743, 2024). "We first verified that MyD88 molecule was essential for CpG-mediated attenuation of the allergic reaction, ruling out the participation of TRIF pathway in this process." (PMID 32391011, 2020). "ES-62 is a secreted parasitic worm-derived immunomodulator that exhibits therapeutic potential in allergy by downregulating aberrant MyD88 signalling to normalise the inflammatory phenotype and mast cell responses." (PMID 29540770, 2018). "The mechanisms of action involved in these therapeutic processes are not well understood; however, it is known that DNAhsp65 stimulates MyD88 signaling, and that CpG activates Fas molecules, culminating in IFN-γ and IL-10 production and reducing allergy." (PMID 35047886, 2020). "In the jejunum of mice experiencing allergic reactions, the TLR-4 gene may similarly be activated by allergens, interacting with MYD88 to initiate a cascade of immune and inflammatory responses, thereby influencing the physiological state of the jejunum." (PMID 40870825, 2025). "Repetitive exposure to ODE did not induce an increase in the Th2 cytokines IL-4, IL-5, and IL-13 which are known to be involved in the classical allergy response and agrees with the lack of MyD88 involvement in regulating serum IgE levels." (PMID 32321514, 2020). "Now in this study, we found that cGAMP functions as an allergy-prone adjuvant inducing strong type-2 immune responses to co-inhaled allergen in the airway which was dependent on IL-33 and its receptor ST2, which utilize MyD88-dependent signaling pathway." (PMID 31616416, 2019). "The higher allergy risk has been linked in numerous studies with the lack of pathogen-recognition receptors such as toll like receptors 4, TRIF and MyD88." (PMID 30323863, 2018). "The MYD88 and TLR-4 genes are pivotal in immune signal transduction and inflammatory responses, and their interaction may dictate the intensity and progression of allergic reactions." (PMID 40870825, 2025). "In response to these proteins, it is not a specific allergy that is important, but the phenomenon of the induced hypersensitivity pathways and the MyD88-ROR-γt axis defect, which may be congenital or secondary to dysbiosis." (PMID 36230344, 2022). "Notably, transfer of cells from DNAhsp65- or CpG/CFP immunized MyD88−/− knockout mice failed to reduce allergy." (PMID 35047886, 2020).
Alzheimer disease (12 papers, 2011 to 2024). A progressive, neurodegenerative disease characterized by loss of function and death of nerve cells in several areas of the brain leading to loss of cognitive function such as memory and language. "We have found that TLR2 and MyD88 levels are elevated in the hippocampus and cortex of patients with Alzheimer’s disease (AD) and in a 5XFAD mouse model of AD." (PMID 29990310, 2018). "It has been shown that the TLR4/myeloid differentiation primary response 88 (MyD88)/nuclear factor (NF‐kB) signalling pathway mediates neuroinflammation in CNS diseases such as Alzheimer's disease (AD), Parkinson's disease (PD), subarachnoid haemorrhage (SAM) and vascular dementia." (PMID 35393774, 2022). "EX inhibited the phosphorylations MAPKs, nuclear factor κB (NF-κB), myeloid differentiation factor 88(MyD88), cathepsin B. In conclusion, these results suggest that EX may be a potential agent for treating Alzheimer’s disease." (PMID 28582770, 2017). "Interestingly, in a mouse model of Alzheimer's disease, MyD88 deficient and APP over-expressing mice had an accelerated disease process pointing to a role for MyD88 in clearance of amyloid." (PMID 22363497, 2012). "MyD88 present in bone-marrow hematopoietic cells has been demonstrated to be neuroprotective in an animal model of amyotrophic lateral sclerosis, although bone-marrow-derived cells lacking MyD88 improve Alzheimer's disease-like pathology in two different mouse models of the disease." (PMID 21989292, 2011).